CDC26 (cell division cycle 26)
Description:
Component of the anaphase promoting complex/cyclosome (APC/C), a cell cycle-regulated E3 ubiquitin ligase that controls progression through the cell cycle. Together with the RING-H2 protein ANAPC11, forms the catalytic component of the E3 ubiquitin ligase complex. APC/C acts by mediating ubiquitination and subsequent degradation of target proteins: it mainly mediates the formation of 'Lys-11'-linked polyubiquitin chains and, to a lower extent, the formation of 'Lys-48'- and 'Lys-63'-linked polyubiquitin chains. APC/C catalyzes assembly of branched 'Lys-11'-/'Lys-48'-linked branched ubiquitin chains on target proteins. APC/C is activated by CDC20 in the metaphase/anaphase transition of cell cycle, targeting the degradation of cyclin B and securin. APC/C is regulated by the mitotic checkpoint complex (MCC), which inhibits APC/C and delays chromosome segregation. May recruit the E2 ubiquitin-conjugating enzymes to the complex.
Synonyms: APC12; ANAPC12; C9orf17
Tractability: PROTAC: its protein half-life has been measured.
Gene: Protein-coding gene on chromosome 9 (113,255,835 to 113,275,602, reverse strand). Ensembl gene ENSG00000176386.
Subcellular location: Nucleus
Subcellular location (Human Protein Atlas): Nucleoplasm
Pathways (Reactome):
Cell Cycle: APC-Cdc20 mediated degradation of Nek2A; APC/C:Cdc20 mediated degradation of Cyclin B; APC/C:Cdc20 mediated degradation of Securin; APC/C:Cdc20 mediated degradation of mitotic proteins; APC/C:Cdh1 mediated degradation of Cdc20 and other APC/C:Cdh1 targeted proteins in late mitosis/early G1; Autodegradation of Cdh1 by Cdh1:APC/C; Cdc20:Phospho-APC/C mediated degradation of Cyclin A; Conversion from APC/C:Cdc20 to APC/C:Cdh1 in late anaphase; Inactivation of APC/C via direct inhibition of the APC/C complex; Phosphorylation of the APC/C; Regulation of APC/C activators between G1/S and early anaphase; Separation of Sister Chromatids
DNA Replication: Assembly of the pre-replicative complex; CDK-mediated phosphorylation and removal of Cdc6
Cellular responses to stimuli: Senescence-Associated Secretory Phenotype (SASP)
Disease: Aberrant regulation of mitotic exit in cancer due to RB1 defects
Gene expression (Transcription): Transcriptional Regulation by VENTX
Immune System: Antigen processing: Ubiquitination & Proteasome degradation
Gene Ontology:
Molecular function: protein binding
Biological process: anaphase-promoting complex-dependent catabolic process; protein branched polyubiquitination; protein K11-linked ubiquitination; protein K48-linked ubiquitination; regulation of meiotic cell cycle; regulation of mitotic cell cycle; protein ubiquitination
Cellular component: anaphase-promoting complex; cytosol; nucleoplasm; nucleus
Genetic constraint (gnomAD): Loss-of-function variants: 1 observed, 2.42 expected, observed/expected ratio (o/e) 0.41, 90% interval 0.14 to 1.64. That is too few expected variants to judge how well the gene tolerates losing a copy. Missense variants: 21 observed, 26.56 expected, observed/expected ratio (o/e) 0.79, 90% interval 0.56 to 1.14. Synonymous variants: 5 observed, 7.09 expected, observed/expected ratio (o/e) 0.71, 90% interval 0.37 to 1.46.
Homologues: Orthologues: chimpanzee CDC26 (100% identical), macaque CDC26 (99% identical), pig CDC26 (96% identical), dog CDC26 (94% identical), guinea pig CDC26 (94% identical), rabbit CDC26 (93% identical), rat Cdc26 (89% identical), mouse Cdc26 (88% identical), tropical clawed frog cdc26 (69% identical), rat LOC103692897 (65% identical), zebrafish cdc26 (62% identical).
Diseases named in the same sentence as CDC26 in open-access papers:
CDC26 is named in the same sentence as 7 diseases in open-access papers, as found by Europe PMC text mining. Sharing a sentence is not in itself a finding about the gene and the disease. The quoted sentences say what the papers report.
gastric cancer (1 paper, 2020). A primary or metastatic malignant neoplasm involving the stomach. "To understand the mechanism underlying the cell cycle arrest of gastric cancer cells induced by knocking down AURKB, we next examined the effect of AURKB on various key cell cycle regulatory molecules, including CCND1, CDC16, CDC6, CDC26, CCNB2, CCNF, p27 and E2F1, in gastric cancer cells." (PMID 31982864, 2020).
pancreatic cancer (1 paper, 2019). "Additionally, a study on pancreatic cancer and CDC26 showed that CCDC26 was responsible for the growth and apoptosis of pancreatic cancer cells, partly by regulating PCNA and Bcl2 expression." (PMID 31619233, 2019).
CDC26 also shares sentences with these, for which no sentence is quoted: cancer (3 papers); Alzheimer disease (1); bladder cancer (1); infection (1); viral infection (1).